TNF (tumor necrosis factor)
Diseases named in the same sentence as TNF in open-access papers (continued):
Sharing a sentence is not in itself a finding about the gene and the disease.
Cognitive impairment (continued). "In terms of neuroinflammation, PFOA exposure caused an increase in the LPS content and TNF-α levels in the mouse cortex, which led to cognitive deficits and dysbiosis with the gut and brain." (PMID 38250995, 2024). "Interleukin-6 (IL-6), tumor necrosis factor-a (TNF-a), and C-reactive protein have been shown to be linked to cognitive impairment, and changes in peripheral CD4+, CD8+, CD3+, and CD4+/CD3+ levels have been documented." (PMID 38322584, 2024). "Studies in mice and humans reported that NK cells from AD patients are more reactive, observing an increase in the production of IFN-γ and TNF-α, which is associated with a significant cognitive impairment." (PMID 39000512, 2024). "QCLG improved weight loss, cognitive impairment, neurological function scores, blood ammonia, and brain gene expression of interleukin-6 (TNF-α), Interleukin-1β (IL-1β), and interleukin-6 (IL-6) induced by HE." (PMID 39220284, 2024). "First, sarcopenia and cognitive disorders share similar risk factors as follows: inflammation, characterized by interleukin-6 (IL-6) and tumor necrosis factor-α; oxidative stress; hormonal changes; and malnutrition." (PMID 36837864, 2023). "A few studies also identified imbalances in TNF-α, IL-1, and IL-6 as being implicated in mood and cognitive impairments." (PMID 38138916, 2023). "Megasphaera is associated with cognitive impairment and inflammation in patients with hepatic encephalopathy, while increased Lactobacillus is associated with TNF production and intestinal inflammation." (PMID 37371865, 2023). "Cognitive impairment, represented by reduced place recognition memory that is accompanied by hippocampal upregulation of mRNA levels of IL-1β, IL-6, and TNF-α, has also been recently observed in HFD and fiber-deficient diet mice." (PMID 37432552, 2023). "We aimed to examine the association of CSF tumor necrosis factor-alpha (TNFα) with conversion from mild cognitive impairment (MCI) to dementia." (PMID 36288380, 2022). "High level of NO in the brain was associated with elevated levels of interleukin-6 and tumor necrosis factor-α, both of which can contribute to cognitive impairment through tau phosphorylation." (PMID 35911235, 2022). "According to recent studies, TNF-α level is associated with memory and cognitive impairment indicates memory defect, which is a characteristic feature of AD pathophysiology." (PMID 36281465, 2022). "As the main inflammatory cells in the CNS, microglia and astrocytes secrete several pro-inflammatory factors, such as IL-33, TNF-α, IL-1β, IL-18, IL-6, ROS, and NO, leading to neuroinflammation, which is thought to be associated with cognitive impairment." (PMID 35974336, 2022). "Patients with first-episode schizophrenia have remarkably increased expression levels of serum TNF-α and iNOS, which is associated with cognitive impairment and disease burden." (PMID 36246695, 2022). "The activation of microglia facilitates the increase of hippocampal neuroinflammatory cytokine levels (interleukin-1β [IL-1β], IL-6, and TNF-α [tumor necrosis factor α]) and finally causes cognitive impairment." (PMID 36104739, 2022). "Tumor necrosis factor (TNF), one of the key components in neuroinflammation secreted by activated microglia, is verified to be associated with cognitive impairment." (PMID 35370905, 2022). "Patients with schizophrenia have up-regulated expressions of serum TNF-α and iNOS, which is associated with the cognitive impairment and disease burden of such patients." (PMID 36246695, 2022). "TNF-α and IL-6 were negatively associated with MMSE score, and high TNF-α, IL-1β, and IL-6 were correlated with cognition impairment occurrence." (PMID 35239774, 2022). "Higher serum levels of CA-125, FABP, and TNF-alpha as well as lower serum levels of BDNF were associated with cognitive impairment as measured by MoCA scores and with motor impairment assessed by H&Y staging in males and/or females." (PMID 35280273, 2022).
Cognitive impairment (continued). "TNFα induced the activation of NF-κβ signaling pathway and caspase 3 was associated with diabetic-induced cognitive deficits and insulin combination with tocotrienol exhibited promising cognitive enhancement in the diabetic rats." (PMID 34108878, 2021). "Elevated serum levels of proinflammatory cytokines, including interleukin 6 (IL-6), tumor necrosis factor-alpha (TNF-α), and C-reactive protein, can cause cognitive impairment." (PMID 33627087, 2021). "After adjustment for age and sex, PD-cognitive deficit was positively associated with plasma EV pro-IL-1β, IL-6, TNF-α, and IL-10 levels and negatively with the TGF-β1 level." (PMID 33803292, 2021). "These cells further stimulate the production of the cytokines such as IL‐1, IL‐6, and tumor necrosis factor α (TNF‐α) which have also been associated with cognitive impairment." (PMID 32896023, 2021). "The immune-neurotoxicity of peripheral TNF-α is associated with psychotic symptoms and cognitive deficits of schizophrenia patients." (PMID 34526062, 2021). "Remarkably, P. gingivalis infection caused TNF-α and IL-1β expression in the brain tissues, resulting in cognitive impairment in middle-aged mice." (PMID 34831265, 2021). "Many inflammatory biomarkers such as interleukin-1 and tumor necrosis factor alpha are thought to be associated with mood disorder and cognitive impairment." (PMID 33517931, 2021). "IL-1β has similar functions as TNF-α, which is associated with mTBI-related cognitive impairment in acute working memory." (PMID 35153973, 2021). "Proinflammatory cytokines, such as TNF-α and IL-6, are associated with neuroinflammation and lead to cognitive impairment following surgery under cbupivacine anesthesia." (PMID 33179100, 2021). "They examined the cross-sectional and longitudinal associations between baseline-measured IL-6, IL-10, and tumor necrosis factor (TNFα) levels in the blood and the ratio of IL-6/IL-10 with cognitive test performance and mild cognitive impairment." (PMID 32455758, 2020). "A neuropathology that involves TNFα-mediated neuroinflammation and Pgrmc1 signaling is Alzheimer’s disease (AD), a progressive neurological disease that results in cognitive impairment and memory loss." (PMID 31026287, 2019). "Significant associations were established between postural instability and serum TNFα levels (P < 0.001) and between postural dizziness and serum NOx levels (P < 0.001), while low serum NOx levels was associated with cognitive impairment (P < 0.001)." (PMID 30954070, 2019). "Its activation eventually increases level of pro-inflammatory cytokines in brain, such as TNF-α and IL-6, which subsequently cause cognitive impairment." (PMID 31759387, 2019). "On the other hand, elevated TNF-α levels in the cerebrospinal fluid of pediatric victims of malaria was only associated with neurological and cognitive deficits." (PMID 31878288, 2019). "The cytokines IL-1β and TNF-α are widely described neuroinflammatory mediators associated with cognitive impairment." (PMID 28724382, 2017). "The peripheral immune system can be activated by surgical injury, leading to the release of various inflammatory cytokines including tumor necrosis factor-alpha (TNF-α), which can diffuse through the blood–brain barrier and cause cognitive deficits." (PMID 28599629, 2017). "A more recent study showed that, in various experimental models, including monkeys, intra-cerebroventricular injection of Aβ oligomers induced PKR and eIF2α phosphorylation along with cognitive deficits via a mechanism linked to TNFα production." (PMID 28982375, 2017). "Pro-inflammatory cytokines, particularly IL-1β, TNF-α and IL-6, are associated with cognitive impairment." (PMID 29238302, 2017). "It has been reported that pro-inflammatory cytokines, such as TNF-α, IL-1β, and IL-6, are associated with cognitive impairment." (PMID 28086911, 2017).
Cognitive impairment (continued). "Studies indicate that high levels of the proinflammatory cytokines interleukin 1-β (IL1-β) and tumor necrosis factor-α (TNF-α) are associated with postoperative cognitive impairments." (PMID 28832497, 2017). "Cognitive deficits and blood–brain barrier damage were associated with early induction of TNFα and Fas mRNA and/or protein, NF-κB-binding activity and activation of microglia and astrocytes." (PMID 25887955, 2015). "AβO-induced abnormal hippocampal TNF-α signaling was found to be directly linked to synapse deterioration and cognitive impairment." (PMID 25617315, 2015). "The current study confirms the rapid generation and release of TNF-α in a mouse closed head 50 g weight drop mTBI model, emulating a concussive head injury in humans, which led to neuronal loss and specific cognitive deficits." (PMID 25879458, 2015). "Preclinical AD models demonstrate the deleterious role of TNFα in AD-associated pathogenesis and cognitive deficits." (PMID 22632257, 2012). "CPB evokes an inflammatory response marked by inflammatory mediators such as interleukine-6, interleukine-1β and tumor necrosis factor α, that are associated with blood–brain barrier disruption and neuroinflammation, leading to neuronal damage and cognitive impairment." (PMID 40725816, 2025). "Specifically, an early increase in the levels of pro-inflammatory cytokines TNF-α, IL-6 and IL-1β was generally observed across studies (measured in the hippocampus and/or plasma), with these increases being associated with the cognitive impairments observed in the animals." (PMID 41155372, 2025). "T. gondii infection induces the synthesis and upregulation of proinflammatory cytokines such as interleukin (IL)-6, IL-8 and tumor necrosis factor alpha (TNF-α), biomarkers of chronic inflammation associated with aging, neurodegenerative disorders and cognitive impairment." (PMID 41018675, 2025). "Persistent immune activation, cytokine release (e.g., IL-6, TNF-α), and microglial activation have been linked to neuroinflammation, which may contribute to fatigue, headaches, and cognitive impairment." (PMID 40217997, 2025). "In 2VO rats, this formula (500 mg/kg, 42 days) improved cognitive impairment in Morris water maze, ameliorated white matter lesions and reduced neuron loss in the cortex and hippocampus, decreased the release of IL-6, TNF-α, MCP-1, and IL-33 in the cerebrospinal fluid and in plasma." (PMID 41230091, 2025). "SAR, however, markedly diminished the duration spent in one square, indicating an anxiolytic effect mediated by PPARγ’s capacity to inhibit pro-inflammatory cytokines like TNF-α and IL-6, which are implicated in neuroinflammation-related anxiety and cognitive impairment." (PMID 40863337, 2025). "TNF-α and IL-1β are potent proinflammatory cytokines that induce neuronal death and cause sensory and cognitive deficits by mediating peripheral synaptic instability, whereas the inhibition of TNF-α and IL-1β has been associated with the alleviation of cognitive dysfunction." (PMID 39630234, 2025). "It has also been hypothesized that TNF-α reduces cerebral perfusion, leading to frontal and parietal hypoperfusion, which in turn causes cognitive impairment." (PMID 40291023, 2025). "Both TNF-α and IL-1β are associated with cognitive impairment." (PMID 40017811, 2024). "P. gingivalis periodontal infection may cause cognitive impairment or neuroinflammation via the release of the pro-inflammatory cytokines IL-6, TNF-α, and IL-1β." (PMID 38764065, 2024). "However, NDR kinases have been associated with the regulation of established SASP components, such as Tumor necrosis factor-alpha (TNF-α) which has been implicated in the heightened neuroinflammatory response and cognitive impairment during aging." (PMID 38803357, 2024).
Cognitive impairment (continued). "Brain‐derived neurotrophic factor (BDNF) and tumor necrosis factor alpha (TNFα) levels, demyelination scores in the corpus callosum (CC), and cognitive impairment were evaluated using the enzyme‐linked immunosorbent assay, histological, and Y‐maze tests, respectively." (PMID 37403256, 2023). "To investigate whether inflammation is associated with cognitive impairment, we measured hippocampal expression of cytokines IL-1β, IL-6, and TNF-α." (PMID 37091543, 2023). "Together, these data indicate that IL-1β may be more closely linked to anxiety-like mood and sleep disorders, while TNF-α may be linked to depressive mood and cognitive abnormalities, which aligns with our findings." (PMID 37692303, 2023). "Excessive TNF-α in brain tissue disrupts Aβ clearance mediated by brain microglia resulting in increased Aβ protein accumulation, causing synaptic dysfunction, thereby speeding up disease development and cognitive impairment." (PMID 35813949, 2022). "At present, whether TNF-α mediates pain-associated cognitive deficits by activating necroptosis remains unclear; however, its role has been reported in other neurodegenerative diseases." (PMID 35806192, 2022). "Also, increased TNF-α and IL-6 are correlated with high risk of mild cognitive impairment in type 2 diabetes patients." (PMID 35239774, 2022). "Of note, TNF-α is elevated in several neurological diseases associated with memory and learning deficits and plays an important role in age-related cognitive decline and in Alzheimer disease-induced cognitive impairment." (PMID 36078036, 2022). "Furthermore, to our knowledge, this is the first study to report an association between pro-inflammatory cytokines, IL-6 and TNFα and low vegetable consumption in elderly with mild cognitive impairment." (PMID 35052306, 2022). "In addition, a study dealing with LPS-induced cognitive impairment and neuroinflammation showed the interconnection of microglia activation and neuronal cell loss with increased NO and TNF-α production." (PMID 34539802, 2021). "Moreover, reduced serum Ahsg levels in patients with mild to moderate Alzheimer's disease were associated with cognitive impairment and high levels of TNF-α." (PMID 34007409, 2021). "TNF-α and IL-6 are pro-inflammatory cytokines that are associated with cognitive impairment." (PMID 34248475, 2021). "Peripheral inflammation is positively associated with cognitive decline and could detrimentally impact brain function; specifically, elevated systemic TNF levels have been associated with increased conversion of mild cognitive impairment to AD." (PMID 34243793, 2021). "Whilst our findings are particularly novel in terms of the population studied (a middle-aged population free from T2DM complications), they are in-keeping with previous studies which have demonstrated cross-sectional associations of TNF-α levels with cognitive impairment in older adults with T2DM." (PMID 33424582, 2020). "Recently, it has been reported that anti-TNF-α treatment can improve cognitive impairment in rats caused by chronic hyperammonemia-induced peripheral and central nervous system inflammation that can lead to neurotransmission and cognitive impairment." (PMID 31596729, 2019). "The increased levels of IL-6, TNF-α are associated with increased Aβ production, decreased Aβ clearance, tau hyper phosphorylation, synaptic dysfunction, and cognitive deficits." (PMID 31680874, 2019). "We know that risk for conversion from mild cognitive impairment to the dementia stage of AD is increased in patients with elevated concentrations of the pro-inflammatory cytokine TNF-α and decreased concentrations of anti-inflammatory transforming growth factor beta (TGF-β) in the CSF." (PMID 31277647, 2019). "Therefore, prior neurodegeneration in the ME7 model is a risk factor for acute cognitive deficits following acute systemic elevation of TNF-α." (PMID 27633985, 2017).
Cognitive impairment (continued). "High concentrations of IL1-β and TNF-α in the brain are associated with cognitive impairments." (PMID 28832497, 2017). "Alterations in excitability and synaptic plasticity, specifically in LTP, may underlie the cognitive deficits that are so typical of AD and pathological TNFα signaling may contribute to such impairments." (PMID 27672476, 2016). "We hypothesize that the brain-wide increases in TNFα and other cytokines occurring with exposure to air pollution contribute to the cognitive deficits that have been epidemiologically associated with air pollutants." (PMID 27187980, 2016). "Furthermore, we have previously shown that ASK1 deficiency caused the amelioration of cognitive impairment in mice subjected to chronic cerebral hypoperfusion, through the suppression of cerebral hypoperfusion-induced white matter lesion or TNF-α induction." (PMID 26044555, 2015). "Therefore, collectively, ASK1 appears to be involved in cognitive impairment caused by long-term high-fat diet feeding, through cerebral hypoperfusion-induced white matter or hippocampal injury and TNF-α induction." (PMID 26044555, 2015). "The reduction of TNFα by naringenin is presumed to occur through the modulation of signaling pathways linked to microglial activation, indicating its potential to interfere with the neuroinflammatory cascades responsible for hippocampal injury and cognitive impairments." (PMID 40486726, 2025). "Interestingly, some studies have demonstrated that the levels of CD8+ T cells, Tregs, and TNF-α are linked to cognitive impairment in PD patients and could act as potential markers for PD onset." (PMID 39860410, 2025). "Cognitive deficits and AD-related cognitive decline in DS individuals are associated with neuroinflammation, a deficit of neurotrophic factors and an “inflammatory endophenotype” with increased concentrations of pro-inflammatory cytokines (e.g., IL-1 and TNF-α)." (PMID 38576478, 2024). "In addition, in young individuals with DS, we found, for the first time, a negative correlation between low TGF-β1 concentrations and high TNF-α plasma concentrations, a pro-inflammatory cytokine that is known to be associated with cognitive impairment in DS individuals with AD." (PMID 38576478, 2024). "However, the change of serum netrin-1, along with the association among netrin-1, cognitive impairment and serum cytokines (IL-17 and TNF-α) in AD/MCI patients remains unclear." (PMID 35250531, 2021). "In addition, the association among netrin-1, cognitive impairment and serum inflammatory cytokines such as interleukin-17 (IL-17) and tumor necrosis (TNF-α) remains unclear." (PMID 35250531, 2021). "Unlike the disparities observed in studies with TNF-KO mice, TNF-overexpressing mice, with (Tg6074) or without (TgK3) neurological alterations, are impaired in the MWMT, implying that TNF-driven neuroinflammation might be more consistently associated with cognitive impairment." (PMID 33803476, 2021). "Notably, this TNF-induced molecule sensitizes neurons to toxic effects of amyloid, promotes phenotypic changes in glia, induces CNS chemokines production, and has been implicated in cognitive deficits." (PMID 31892368, 2019). "Thus, it cannot exclude that the increased TNFα may cause the cognitive impairment and anxiety-like behavior by directly destroying the blood-brain barrier integrity." (PMID 28300056, 2017). "Given that recent studies have suggested that isoflurane may induce neuroinflammation which may be associated with cognitive impairment, we examined with Western blot assays the effects of isoflurane and propofol on the proinflammatory cytokines, TNF-α, IL-1β and IL-6, in the cortex at P7." (PMID 24932894, 2014). "IL-6, TNF-α, and IL-1β levels during chronic neuroinflammation or cognitive impairment represent chronic neuroinflammation or cognitive impairment." (PMID 41516374, 2026).